CCL11 (C-C motif chemokine ligand 11)
Diseases named in the same sentence as CCL11 in open-access papers (continued):
Sharing a sentence is not in itself a finding about the gene and the disease.
Alzheimer disease (23 papers, 2015 to 2025). A progressive, neurodegenerative disease characterized by loss of function and death of nerve cells in several areas of the brain leading to loss of cognitive function such as memory and language. "Increased CCL-11 levels including in old age are associated with neurodegeneration, reduced neurogenesis and an increased risk of Alzheimer’s disease." (PMID 32887304, 2020). "This is important, because the association between CCL-11 and hippocampal damage in aging may be important to understand the pathophysiology of Alzheimer’s disease and old-age depression." (PMID 32887304, 2020). "Interestingly, plasma levels of CCL11 are negatively associated with memory function in patients with Alzheimer’s dementia and older adults dwelling in rural communities." (PMID 33197235, 2020). "As similar findings have been reported in neurodegenerative conditions such as Alzheimer's disease, it has been hypothesized that mechanisms involving eotaxin-1/CCL11 signaling may underlie the “accelerated aging” profile commonly linked to psychiatric disorders." (PMID 29962972, 2018). "The association of a protective haplotype with a 10-year delay in the onset of Alzheimer’s disease and the identification of a CCL11 variant with possible functional roles in this association might allow the future development of immunomodulators with the potential to halve disease incidence." (PMID 26482651, 2015). "A collection of studies showed that plasma CCL11 increased in patients with Alzheimer's disease and Huntington's disease, while it decreased in amyotrophic lateral sclerosis and secondary progressive multiple sclerosis." (PMID 36660076, 2022). "In diseases of old age, CCL-11 is associated with lowered neurogenesis and neurodegenerative processes, and as a consequence, increased CCL-11 increases risk towards Alzheimer’s disease." (PMID 32887304, 2020). "In humans, altered CSF and plasma levels of CCL11 have been observed in Alzheimer's disease (AD), amyotrophic lateral sclerosis (ALS), Huntington's disease (HD) and secondary progressive multiple sclerosis (SPMS) when compared to age-matched, healthy controls." (PMID 28950005, 2017). "CTACK (CCL4), MIG (CXCL9), GROa (CXCL1), MIP-1b (CCL4), Eotaxin (CCL11) and IL-8 belong to the chemokine family and evidence suggest that they could potentially play a role in Alzheimer’s disease." (PMID 35580794, 2022). "Increased CCL-11 production in the course of immune-mediated inflammatory conditions may play a role in age-related cognitive decline, schizophrenia, mood disorders, Alzheimer’s disease, OCD and ASD." (PMID 32887304, 2020). "CCL11, a protein previously associated with age-associated cognitive decline, is observed to be increased in the brain and cerebrospinal fluid (CSF) in chronic traumatic encephalopathy (CTE) compared to Alzheimer’s disease (AD)." (PMID 28950005, 2017). "Furthermore, elevated levels of CCL11 have been observed in several neurodegenerative diseases in humans, such as Alzheimer’s disease and Huntington’s disease." (PMID 29088099, 2017). "Increased levels of CCL-11 have been detected in numerous neuro-inflammatory disorders such as multiple sclerosis, as well as neurodegenerative and neuroprogressive disorders including Alzheimer’s disease and psychiatric illnesses including major depression, bipolar disorder and schizophrenia." (PMID 32887304, 2020). "Notable exceptions include CCL11 that has recently been shown to impair hippocampal function in aging – of distinct relevance to Alzheimer’s disease and depression in the elderly, and pre-natal exposure to CXCL8 that may disrupt early neurodevelopmental periods predisposing to schizophrenia." (PMID 26441528, 2015). "CCL11 is a ligand for the chemokine receptor type 3 (CCR3) receptor and, thus, CCR3 has been identified as a potential therapeutic target for Alzheimer’s disease that reduces amyloid beta deposition and tau phosphorylation." (PMID 37280551, 2023).
Alzheimer disease (continued). "In line with the indirect findings implicating eotaxin-1/CCL11 in “accelerated aging” in bipolar disorder and schizophrenia, elevated plasma levels of eotaxin-1/CCL11 have been observed in neurodegenerative diseases, mainly Alzheimer's disease." (PMID 29962972, 2018).
breast carcinoma (22 papers, 2013 to 2025). "In the 4T1 cohort, CCL11, a chemokine also known as Eotaxin that selectively recruits eosinophils and is associated with increased immune cell infiltration in breast cancer, was significantly higher in the combination treatment group than in IgG isotype controls (p = 0.0161)." (PMID 39623404, 2024). "Indeed, CCL2 and CCL11 have been implicated in several cancers, including breast cancer etiology and metastasis." (PMID 29879116, 2018). "We also noted the downregulation of CCL11 in Subtype 2, which is a well-documented immune cell proliferator, particularly in breast cancer tissue." (PMID 40004168, 2025). "In breast cancer patients, elevated serum CCL11 levels correlate with the expansion of CD4+CD25+Foxp3+Tregs and the enhanced production of IL-2 and TGF-β1 through STAT5 signaling pathway activation." (PMID 40429807, 2025). "Studies indicate a high expression of CCL11 in breast cancer tissues, correlating with improved patient prognosis." (PMID 38305920, 2024). "CCL11 expression correlates with immune cell infiltration in breast cancer, indicating its potential as a prognostic biomarker for BRCA." (PMID 38305920, 2024). "Breast cancer samples were divided into high-expression group and low-expression group according to the median expression level of CCL11." (PMID 38305920, 2024). "An analysis of the TCGA database revealed significant upregulation of CCL11 in breast cancer tissues versus adjacent normal tissues." (PMID 38305920, 2024). "Given that CD4 + CD25 + Foxp3 + is the predominant Treg phenotype, we utilized hospital cohort breast cancer samples for IHC testing of CCL11, CD4, and Foxp3 proteins." (PMID 38305920, 2024). "We also showed that CCL11 inhibits breast cancer cell carcinogenesis by modulating the AKT/S6 pathway, indicating its potential as a drug target." (PMID 38305920, 2024). "The objective of this study was to investigate the biological significance of CCL11 in TME of breast cancer." (PMID 38305920, 2024). "Higher immune and stromal scores were observed in the group with high CCL11 expression compared to the low-expression group, suggesting CCL11's influence on immune activity within the breast cancer TME." (PMID 38305920, 2024). "In summary, our study demonstrated that CCL11 is a potential independent prognostic biomarker with a tumor-suppressive function in breast cancer." (PMID 38305920, 2024). "Addition of CCL11 to breast cancer cells significantly inhibited proliferation, colony formation, migration, and invasion, suggesting a tumor-suppressive effect of CCL11." (PMID 38305920, 2024). "We further assessed CCL11's role in breast cancer progression by examining its effects on cell migration and invasion." (PMID 38305920, 2024). "The high CCL11 level was shown to increase the proportion of immunosuppressive CD4+CD25+Foxp3+ Tregs in a breast cancer model, indicating the pro-tumoral effect of the IL-4/CCL11 interaction." (PMID 37445941, 2023). "The administration of a DPP4 inhibitor in mice with subcutaneous EMT6 breast cancer cell implantation induced intratumoral accumulation of CCL11, resulting in eosinophilic chemotaxis and reduced tumor growth." (PMID 34572273, 2021). "For example, a hypoxic area in a human breast cancer specimen demonstrates higher levels of CCL11 and a higher number of TAMs compared with a normoxic area." (PMID 30483271, 2018). "Since MDA-MB-231 breast cancer cells under hypoxic conditions increase CCL11 secretion and thereby promote macrophage migration in vitro, these results suggest that CCL11 is induced by low oxygen and locally recruits TAMs to the hypoxic regions in tumors." (PMID 30483271, 2018). "DPP4 inhibition (using the anti-diabetic medication, sitagliptin) in a pre-clinical syngeneic mouse model of breast cancer has been shown to increase CCL11 levels, eosinophil infiltration and improve tumor control and was synergistic with immune checkpoint inhibition." (PMID 40428397, 2025).
breast carcinoma (continued). "Validation studies confirmed high CCL11 expression in breast cancer tissues." (PMID 38305920, 2024). "Thus, further investigation into CCL11's role and prognostic value in the context of immunotherapy is warranted to determine its potential as a therapeutic target for breast cancer." (PMID 38305920, 2024). "Next, we analyzed the biological function of CCL11 in breast cancer through cellular experiments." (PMID 38305920, 2024). "It was found that miR-29b could inhibit breast cancer cell survival and also suppressed cell growth by CCL11 and CXCL14 stimulation." (PMID 28465475, 2017). "Breast cancer cell invasion ability was also inhibited by miR-29b, which could suppress CCL11 and CXCL14 enhanced invasion." (PMID 28465475, 2017). "However, it remains unclear whether CCL11 influences tumor progression via TILs in breast cancer's TME." (PMID 38305920, 2024). "MiR-29b could inhibit breast cancer cell migration via CCL11 or CXCL14 from CAFs." (PMID 28465475, 2017). "The TISIDB database heat map showed significant positive correlations between CCL11 expression and various immune-related genes, including immune activators, suppressants, chemokines, receptors, and MHC genes in breast cancer." (PMID 38305920, 2024). "Future work will be required to study the effects of CCL11 and CCL26 on M2 macrophage polarization and the subsequent effect on the migration and invasion of breast cancer cells." (PMID 38554160, 2024). "By targeting CCL11 and CXCL14, MiR-29b encore in CAFs decreases breast cancer cell survival and metastasis." (PMID 36247409, 2022). "Similar with CXCL10, administration of sitagliptin resulted in higher concentrations of bioactive CCL11 in the TME of hepatocellular carcinoma and breast cancer, leading to increased migration of eosinophils into solid tumors." (PMID 33757558, 2021). "In breast cancer models, chronic hypoxia has been shown to increase CCL11/eotaxin-1 expression depending on the induction of oncostatin M expression." (PMID 32781743, 2020). "Of them, CXCL10, CXCL9, CCL11, CCR8, and GNG13 up-regulate breast cancer, while the other genes download-regulate breast cancer." (PMID 31874629, 2019). "We found that fibroblasts activated by co-cultured breast cancer cells produced higher levels of some chemokines like CCL11, CXCL14, which accelerated breast cancer cell growth and induced drug resistance and metastasis." (PMID 28465475, 2017). "CCL11 and CXCL14 from the CAFs will exert on breast cancer cell and then promotes cell proliferation and metastasis." (PMID 28465475, 2017). "Notably, CCL11 has been found to be upregulated in colorectal cancer (CRC), breast cancer, and oral squamous cell carcinomas (OSCC)." (PMID 38305920, 2024). "CCL11, a chemokine known for recruiting immune cells to the tumor microenvironment (TME), has an unclear role in the context of its expression, patient prognosis, and the presence of tumor-infiltrating immune cells (TILs) in breast cancer." (PMID 38305920, 2024). "Compared with healthy volunteers, the extremely high serum levels of MMP-9 and CCL21 in patients with colon cancer, of CCL11 in patients with gastric cancer, of CCL2/MCP-1 in patients with breast cancer and of CXCL13 in patients with liver cancer have been reported." (PMID 31754081, 2019). "Interestingly, a recent report suggests that CCL3 released from E0771 breast cancer cells increases expression of CCL7, CCL8, CCL11, and CCL12 in the lung." (PMID 30483271, 2018). "Here, to know whether there are differences of miR-29b down-regulation on drug resistance of breast cancer cells, MCF-7 cells were treated with CM-CAFs, CM-CAFs/miR-29b-1 or CM-CAFs/miR-29b-2 and exposed to paclitaxel (10uM) or CCL11 or CXCL14." (PMID 28465475, 2017). "Further molecular mechanism exploration indicated CCL11 and CXCL14 could active p38-STAT1 pathway in breast cancer cells." (PMID 28465475, 2017).
colitis (22 papers, 2011 to 2025). Inflammation of the colon. "The levels of IL-4, IL-5, IL-17, and CCL11 were increased in the TA-administered colitis group compared with the unadministered colitis mice, but this increase was not statistically significant." (PMID 40333150, 2025). "CCL11 induces angiogenic responses via its receptor CCR3 in endothelial cells, and the relevance of CCL11 with respect to colitis has been demonstrated." (PMID 35805947, 2022). "Additionally, it examined the expression of CCR3, CCL11, IL-5Rα, and TLRs in TA-treated normal and colitis mice to evaluate the role of TA in enhancing eosinophil-mediated inflammation through the modulation of these receptors and ligands." (PMID 40333150, 2025). "In addition, CCL11 levels are elevated in both the serum and colonic tissues of patients with UC and are also increased in the colitis model." (PMID 40333150, 2025). "However, and in contrast, the DSS-induced colitis caused significantly increased levels of CXCL1, CCL2, CCL3, CCL11, G-CSF, and GM-CSF in Mcpt-4ΔCre mice as compared to Mcpt-4fl/fl mice." (PMID 40697820, 2025). "We found that there were 15 analytes upregulated in both DSS and C. rodentium colitis, including innate immune cell-associated cytokines (G-CSF, IL-1β, TNF-α, LIF, and IL-6), chemokines (CCL2, CCL5, CCL11, CXCL2, CXCL8, CXCL9, MIP-1α, and MIP-1β), and Th1 (IFN-γ) and Th17 (IL-17) cytokines." (PMID 30972302, 2019). "In addition, the mRNA expression of several cytokine/chemokine (IL-6, CXCL1, CCL11, and IL-1β) genes was low in Eng+/− mice at days 18–23 of colitis." (PMID 25114380, 2014). "In our work, the defect of Mcpt-4 gene led to colitis mice producing higher levels of chemokines especially CXCL1, CCL2, CCL3, and CCL11." (PMID 40697820, 2025). "CCL11, also known as eotaxin-1, is considered as an eosinophil chemoattractant, and is involved in the pathogenesis of DSS−induced colitis." (PMID 35893911, 2022). "The mRNA expression levels of Th2 cytokines as well as IL-17, IL-5Rα, and CCL11 were analyzed in TA-treated and TA-non-treated colitis mice." (PMID 40333150, 2025). "More importantly, mesalazine treatment reversed the suppressive effect of immune responsive genes, including chemokine (C–X–C motif) ligand (CXCL3), chemokine (C–C motif) ligand (CCL11 and CCL21), chemokine receptor (CXCR2), and colony-stimulating factor (CSF3) in the DSS-induced colitis model." (PMID 34456974, 2021).
schizophrenia (20 papers, 2015 to 2025). A major psychotic disorder characterized by abnormalities in the perception or expression of reality. "CCL11 promotor polymorphisms (including -426 T/C in three haplotypes) were found to be associated with an increased risk of the development of schizophrenia in the Korean population." (PMID 40149440, 2025). "In schizophrenia, increased CCL-11 is not only associated with impairments in cognitive functions, but also with key symptoms including formal thought disorders." (PMID 32887304, 2020). "Moreover, increased CCL-11 levels are also associated with neurocognitive deficits in aging, neurodegenerative disorders and major psychiatric disorders such as schizophrenia." (PMID 32887304, 2020). "Several studies have reported the association between blood levels of CCL11 and psychiatric disorders, for example in schizophrenia, bipolar disorders, major depression, and psychopathologies with suicidal ideation, but there are no studies in a context of substance use disorders." (PMID 28149283, 2016). "Robust data, supported by meta-analyses, indicate elevated levels of CXCL8/IL-8, CCL2/MCP-1, CCL4/MIP-1β, and CCL11/eotaxin-1 in the bloodstream of individuals with schizophrenia." (PMID 41303622, 2025). "Meta-analyses data showed an increase in CXCL8/IL-8, CCL2/MCP-1, CCL4/MIP-1β, and CCL11/eotaxin-1 in the blood of patients with schizophrenia." (PMID 39457671, 2024). "Plasma levels of CCL-11 are increased not only in schizophrenia and age-related cognitive impairments, but also in some patients with mood disorders and premenstrual syndrome." (PMID 32887304, 2020). "Regarding CCL11, considerable evidence exists on the role of this chemokine in the progression of neurodegenerative diseases (e.g., schizophrenia or dementia patients), but contradictory results have been reported in relation to MDD." (PMID 30870525, 2019). "Increased circulating levels of eotaxin-1/CCL11 have been described in major psychiatric disorders (schizophrenia, bipolar disorder, major depression), sometimes correlating with the severity of psychopathological and cognitive parameters." (PMID 29962972, 2018). "Notably, CCL11 levels areelevated in patients with schizophrenia, major depressive disorder, and bipolardisorder, with this alteration exhibiting similarities across differentpsychiatric conditions." (PMID 40926813, 2025). "Accordingly, targeted therapy to normalize CCL11 levels might develop mental and physical health among patients with schizophrenia and AD." (PMID 37626992, 2023). "Besides, the most reliable data confirmed by the results of meta-analyses showed an increase in CXCL8/IL-8, CCL2/MCP-1, CCL4/MIP-1β, CCL11/eotaxin-1 in the blood of patients with schizophrenia." (PMID 36768537, 2023). "Importantly, MCP-1 (CCL2) serum levels were higher in first-episode psychosis and multiple-episode schizophrenia, while MIP-1β (CCL4) and eotaxin-1 (CCL11) levels were higher only in multiple-episode schizophrenia." (PMID 35546942, 2022). "In a study, the diagnosis of schizophrenia was accompanied by a specific cytokine-chemokine profile, i.e., increased levels of CCL11, CCL3, soluble TNF receptors 1 and 2 (sTNF-R1 and sTNF-R2), and decreased levels CXCL10 (also known as IFN-Υ-inducible protein 10 or IP-10), TNF-α, IL-2, and IL-4." (PMID 28870209, 2017). "In addition, elevated levels of CCL11 are noted in AD and schizophrenia." (PMID 37626992, 2023). "First, in patients with schizophrenia, overactivation of the5-hydroxytryptamine 2A receptor (5-HT2A) triggers upregulation of the eosinophilchemotactic factor Eotaxin-1/CCL11." (PMID 40926813, 2025). "To date, eotaxin-1/CCL11 is considered an endogenous cognitive deteriorating chemokine whose levels are increased in neurodegenerative disorders and schizophrenia." (PMID 31428001, 2019).
schizophrenia (continued). "In this non-systematic mini-review we revisit the actions originally and currently ascribed to eotaxin-1/CCL11, highlighting the emerging role of eotaxin-1/CCL11 in psychiatric disorders, mainly schizophrenia and mood disorders." (PMID 29962972, 2018). "Using five of these biomarkers (sTNF-R1 and sTNF-R2, CCL11, CXCL10, IL-4), the authors found a sensitivity of 70% and specificity of 89.4% for the diagnosis of schizophrenia." (PMID 28870209, 2017). "An independent group corroborated these results, reporting positive correlation between eotaxin-1/CCL11 levels with age, duration of schizophrenia, and severity of negative symptoms." (PMID 29962972, 2018).